SSR1 (signal sequence receptor subunit 1)
Description:
TRAP proteins are part of a complex whose function is to bind calcium to the ER membrane and thereby regulate the retention of ER resident proteins. May be involved in the recycling of the translocation apparatus after completion of the translocation process or may function as a membrane-bound chaperone facilitating folding of translocated proteins.
Synonyms: TRAPA
Tractability: Antibody: UniProt predicts a signal peptide or a membrane-spanning region. PROTAC: ubiquitination databases record sites on it; its protein half-life has been measured.
Gene: Protein-coding gene on chromosome 6 (7,268,306 to 7,347,446, reverse strand). Ensembl gene ENSG00000124783.
Subcellular location: Endoplasmic reticulum membrane
Subcellular location (Human Protein Atlas): Endoplasmic reticulum
Pathways (Reactome):
Cellular responses to stimuli: XBP1(S) activates chaperone genes
Metabolism of proteins: SRP-dependent cotranslational protein targeting to membrane
Gene Ontology:
Molecular function: protein binding
Biological process: cotranslational protein targeting to membrane; positive regulation of cell population proliferation; post-translational protein targeting to membrane, translocation
Cellular component: endoplasmic reticulum; endoplasmic reticulum membrane; membrane; translocon complex
Genetic constraint (gnomAD): Loss-of-function variants: 8 observed, 22.08 expected, observed/expected ratio (o/e) 0.36, 90% interval 0.21 to 0.65. The upper end of that interval is the gene's LOEUF score, 0.65, which puts it in group 2 of 6, group 1 being the genes least tolerant of losing a copy. Missense variants: 235 observed, 284.9 expected, observed/expected ratio (o/e) 0.82, 90% interval 0.74 to 0.92. Synonymous variants: 95 observed, 103.71 expected, observed/expected ratio (o/e) 0.92, 90% interval 0.77 to 1.09.
Homologues: Orthologues: chimpanzee SSR1 (99% identical), macaque SSR1 (99% identical), pig SSR1 (96% identical), dog SSR1 (95% identical), mouse Ssr1 (95% identical), guinea pig SSR1 (95% identical), rat Ssr1 (91% identical), rabbit SSR1 (83% identical), tropical clawed frog ssr1 (81% identical), zebrafish ssr1 (71% identical), Drosophila melanogaster l(1)G0320 (43% identical), Caenorhabditis elegans trap-1 (34% identical).
Diseases named in the same sentence as SSR1 in open-access papers:
SSR1 is named in the same sentence as 25 diseases in open-access papers, as found by Europe PMC text mining. Sharing a sentence is not in itself a finding about the gene and the disease. The quoted sentences say what the papers report.
type 2 diabetes (5 papers, 2015 to 2025). "A trans-ethnic meta-analysis of type 2 diabetes genome-wide association studies has identified seven novel susceptibility variants in or near TMEM154, SSR1/RREB1, FAF1, POU5F1/TCF19, LPP, ARL15 and ABCB9/MPHOSPH9." (PMID 25799151, 2015). "We performed a replication study in a Japanese population to evaluate the association between type 2 diabetes and six susceptibility loci (TMEM154, SSR1, FAF1, POU5F1, ARL15, and MPHOSPH9) originally identified by a transethnic meta-analysis of genome-wide association studies (GWAS) in 2014." (PMID 27115357, 2016). "We examined the association of six SNP loci, rs6813195 near TMEM154, rs9505118 in SSR1, rs17106184 in FAF1, rs3130501 in POU5F1, rs702634 in ARL15, and rs4275659 near MPHOSPH9, identified by transethnic GWAS meta-analysis with susceptibility to type 2 diabetes in a Japanese population." (PMID 27115357, 2016).
glioma (3 papers, 2013 to 2024). A benign or malignant brain and spinal cord tumor that arises from glial cells (astrocytes, oligodendrocytes, ependymal cells). "The findings of this study revealed that circTLK1 mediated by PBX2 regulated JAK/STAT signaling to promote glioma development by facilitating miR-452-5p/SSR1." (PMID 34721518, 2021). "Signal sequence receptor subunit 1 (SSR1) was found to be a downstream target of miR-452-5p in glioma cells." (PMID 34721518, 2021). "Although we partially demonstrated the existence of the novel PBX2/circTLK1/miR-452-5p/SSR1 axis in glioma progression, this will require extensive investigation." (PMID 34721518, 2021). "Investigation of the mechanisms upstream and downstream of circTLK1 revealed that circTLK1 mediated by PBX2 aggravates glioma progression by activating JAK/STAT signaling via the miR-452-5p/SSR1 axis." (PMID 34721518, 2021). "For this purpose, we constructed glioma knockdown cell models and evaluated the expression of SSR1, and JAK/STAT pathway proteins in these cell models were measured." (PMID 34721518, 2021). "CircTLK1 mediated by PBX2 regulates JAK/STAT signaling to promote glioma development via the miR-452-5p/SSR1 axis." (PMID 34721518, 2021). "This suggested that circTLK1/miR-452-5p/SSR1 participates in glioma progression by mediating JAK/STAT signaling." (PMID 34721518, 2021). "Our results revealed that miR-452-5p directly targeted SSR1 and suppressed its expression in glioma cells." (PMID 34721518, 2021). "Taken together, our findings show that circTLK1 mediated by PBX2 activates JAK/STAT signaling to promote glioma progression through the miR-452-5p/SSR1 pathway." (PMID 34721518, 2021). "Furthermore, we found that SSR1 expression in glioma tumor tissues was downregulated and correlated with miR-452-5p or circTLK1 expression." (PMID 34721518, 2021). "CircTLK1 was upregulated in glioma cells, sponging miR‐452‐5p/SSR1, thus facilitating JAK/STAT signaling to stimulate glioma malignancy." (PMID 37953502, 2024). "However, whether SSR1 participates in glioma progression remains unclear." (PMID 34721518, 2021).
breast carcinoma (2 papers, 2021 to 2025). "SSR1 was found to be associated with hypopharyngeal squamous cell carcinoma and breast cancer." (PMID 34721518, 2021). "Cross-correlation analysis of SSR1/RPL39L was found only in colon and lung cancers, and the cross-correlation of PPARGC1B/CDKN2A was found only in colon and breast cancers, R-values of breast, colon and lung data." (PMID 39940786, 2025). "However, there was no cross-correlation between SSR1/RPL39L in breast cancer, although a cross-correlation between SSR1/VARS, VARS/PPARGC1B, and PPARGC1B/RPL39L was found." (PMID 39940786, 2025).
gestational diabetes (2 papers, 2025). Carbohydrate intolerance first diagnosed during pregnancy. "Importantly, GWAS from multiple populations show that polymorphisms in the locus of TRAPα/SSR1 genes are associated with glycemic control defects, including fasting glucose, gestational diabetes, and T2D." (PMID 40392602, 2025).
behavioral disorders (1 paper, 2022). "The expression of SSR1 in peripheral blood began to be upregulated as early as day 3, when behavioral disorders were not obvious." (PMID 35310885, 2022).
colon cancer (1 paper, 2025). "In colon cancer, most likely because of the lack of data, cross-correlation identified only three correlating groups (EIF4E3/MEX3A, SSR1/RPL39L, and PPARGC1B/CDKN2A)." (PMID 39940786, 2025).
hypopharyngeal cancer (1 paper, 2023). Carcinoma, predominantly squamous cell, arising from the epithelial cells of the hypopharynx. "In addition, we reviewed the literature and obtained several biomarkers that may be associated with the prognosis of hypopharyngeal cancer, such as PD-L1, SSR1, S100A4, PCDH20, and α2δ1." (PMID 36941989, 2023).
keloid (1 paper, 2026). An irregularly shaped, elevated mark on the skin caused by deposits of excessive amounts of collagen during wound healing. "Mendelian randomization identified 11 genes causally linked to keloid risk, with genetically determined downregulation of SSR1 and SRA1 associated with increased susceptibility." (PMID 41986576, 2026).
microphthalmia (1 paper, 2023). Congenital or developmental anomaly in which the eyeballs are abnormally small. "A similar search of DR17 using the term microphthalmia resulted in 22 genes significant for the small eyes phenotype: Aldh1a3, Aff4, Bmp4, Cdk4, Cox6b1, Cxcr4, Dync1li1, Eef1d, Fgd1, Gne, Grh12, Mab21l2, Maf, Med13l, Mllt10, Mthfd2, Pex6, Phgdh, Ssr1, Stim1, Tdo2, and Vps26c." (PMID 36737727, 2023).
Parkinson disease (1 paper, 2022). A progressive degenerative disorder of the central nervous system characterized by loss of dopamine producing neurons in the substantia nigra and the presence of Lewy bodies in the substantia nigra and locus coeruleus. "As expected, these curves had AUCs lower than 0.6, which means that SSR1 has extreme specificity to Parkinson’s disease, while it behaves normally in other diseases." (PMID 35310885, 2022).
tumor (3 papers, 2013 to 2021). "The other two target genes, SSR1 and EIF4E, were upregulated through downregulation of miR-483-5p (which plays a tumor promoter or tumor suppressor role, based on cellular context)." (PMID 32204397, 2020).
cancer (1 paper, 2025). A tumor composed of atypical neoplastic, often pleomorphic cells that invade other tissues. "Overexpression of SSR1 in treated cancers may lead to the release of translated genes through the ER rather than to their final destination, where they would usually play specific roles." (PMID 39940786, 2025).
infection (1 paper, 2019). The state of being infected such as from the introduction of a foreign agent such as serum, vaccine, antigenic substance or organism. "The global network notably recognizes six proteins (EPHA2, FBL, PFKM, PSMA5, SSR1, and TFRC) for their involvement in the infection of cells (p: 9.58 × 10− 4)." (PMID 31159726, 2019).
movement disorder (1 paper, 2022). Neurological conditions resulting in abnormal voluntary or involuntary movement, which may impact the speed, fluency, quality and ease of movement. "Therefore, SSR1, which has abnormal expression in the early stage of PD (before obvious movement disorders), can be used not only as an early marker but also as an effective indicator of the severity, progression, and prognosis of PD." (PMID 35310885, 2022).
SSR1 also shares sentences with these, for which no sentence is quoted: diabetes (3 papers); insulinoma (2); COVID-19 (1); fatty liver (1); Glucose intolerance (1); hypopharyngeal squamous cell carcinoma (1); lung carcinoma (1); lupus (1); multiple sclerosis (1); ovarian carcinoma (1); ZIKV infection (1).